MIF (macrophage migration inhibitory factor)
Diseases named in the same sentence as MIF in open-access papers (continued):
Sharing a sentence is not in itself a finding about the gene and the disease.
endometriosis (34 papers, 2012 to 2025). The growth of functional endometrial tissue in anatomic sites outside the uterine body. "We aimed to evaluate the possible association between MIF promoterpolymorphisms and susceptibly to endometriosis and its corolation with mRNA level." (PMID 32347038, 2021). "Nevertheless, our results warrant further investigations to elucidate the possible role of MIF in endometriosis-associated infertility and how MIF could affect reproductive function particularly endometrial receptivity." (PMID 32883256, 2020). "Clearly, studies are warranted to evaluate whether these beneficial effects of ISO-1 can be extended to alleviating the pain associated with endometriosis in animal models with the extension of MIF antagonist into clinical trials." (PMID 26949527, 2016). "Our current data showed that MIF genetic depletion affects ectopic endometrial tissue growth and had a significant impact on several biological pathways closely associated with the pathogenesis of endometriosis." (PMID 25329068, 2014). "This may be the reason for the associationbetween the MIF CATT7/C genotype (haplotype) andthe susceptibility towards endometriosis, because thishaplotype causes the simultaneous presence of AP-4,Pit-1 and ICBP90 transcription factors and consequentlyenhances MIF promoter activity." (PMID 32347038, 2021). "As such, there is ample evidence to suggest a strong association between elevated MIF expression/levels and endometriosisin vivo, as well asin vitro evidence which indicates that MIF can induce factors which are believed to be essential for endometriosis development and survival." (PMID 26949527, 2016). "Elevated serum and tissue MIF levels have been reported in response to estrogen in both rat and human endometrial tissue and endometriosis lesions, which strongly supports our findings." (PMID 40724945, 2025). "The serum MIF concentrations were higher in patients with endometriosis (stages I–IV) than those in healthy controls, even when mild and severe subgroups were analyzed separately." (PMID 40724945, 2025). "Elevated IL-8, C-C chemokine RANTES (CCL5), MCP-1, and MIF attracted more cells in advanced endometriosis lesions in humans and mice." (PMID 40508002, 2025). "MIF is a pro-inflammatory cytokine that promotes inflammation and is found in higher concentrations in women with advanced-stage endometriosis, suggesting its involvement in disease progression." (PMID 40724945, 2025). "MIF and IL-6 were higher in stage I–IV endometriosis, with MIF also higher in the secretory phase and in patients not receiving oral contraceptives." (PMID 40724945, 2025). "A study evaluated, alongside IL-1, another pro-inflammatory cytokine observed in endometriosis, the macrophage migration inhibitory factor (MIF)." (PMID 38337827, 2024). "Some studies have shown that endometriosis is a manifestation of pelvic inflammatory disease, with abundant inflammatory factors in the pathologic examination of endometriosis, such as IL-6, macrophage migration inhibitory factor, TNF-α, IL-1b, IL-6, and IL-8." (PMID 39536051, 2024). "Migration inhibitory factor (MIF) and monocyte chemoattractant protein-1 are two of the most potent factors behind endometriosis-related inflammation." (PMID 36359004, 2022). "Perhaps most relevant to the pathophysiology of endometriosis is the putative cytokine target, macrophage migration inhibitory factor (MIF)." (PMID 35885004, 2022). "Clearly, more detailed assessment of the role of miR-451a, the MIF-pathway and other pathways modulated by miR-451a in the pathophysiology of endometriosis are warranted for study." (PMID 35885004, 2022). "Since endometriosis is an inflammatory disorder andincreased levels of MIF are observed in ectopic tissues,we aimed to evaluate MIF promoter variations thatcould be involved in development of endometriosis andsusceptibility towards this disorder." (PMID 32347038, 2021).
endometriosis (continued). "MIF is one such inflammatory factor that plays a crucial role in the early development of endometriosis." (PMID 34769130, 2021). "Hitherto, TNF-α, PGE2, and MIF (human macrophage migration inhibitory factor) have been proposed for the suppression of inflammation in endometriosis." (PMID 33435569, 2021). "The present study aimed to determine the accuracy of serum MIF in diagnosing endometriosis in women with infertility and chronic pelvic pain, and correlate its level to the stage of the disease." (PMID 32883256, 2020). "Receiver operating characteristics (ROC) curve was used to define the best cut off value of MIF to diagnose endometriosis, which was 0.85 pg/ml or more." (PMID 32883256, 2020). "IL-6, IL-8, and MIF significantly increased in endometriosis cases as compared with the control (p<0.05)." (PMID 33209739, 2020). "Our findings demonstrate the elevated MIF protein production in these patients which is consistent with previous studies that have shown elevated MIF in peritoneal fluid and peripheral blood of women with endometriosis." (PMID 33209739, 2020). "Whilst MCP1 added little to our models, MIF was in the best models for discriminating endometriosis from both control groups, particularly for the secretory phase." (PMID 30992697, 2019). "Building upon these initial observations, several studies have evaluated the efficacy of targeting MIF as a potential endometriosis treatment." (PMID 26949527, 2016). "Initial studies evaluating ISO-1 as a therapeutic agent for endometriosis treatment are encouraging as the MIF antagonist reduces lesion burden in mouse models which harbor both mouse and human tissue, demonstrating efficacy." (PMID 26949527, 2016). "We then discuss emerging data on the role of inter-relationship among macrophage migration inhibitory factor, prostaglandin E2, and estrogen receptor-beta, and the potential utility of targeting these factors in endometriosis treatment." (PMID 26949527, 2016). "Effect of rhMIF add-back in KO mice or specific inhibition of MIF in WT mice on the development of endometriosis-like lesions." (PMID 25329068, 2014). "Based on the current literature and our previous in vitro and in vivo observations, we addressed the role of MIF in establishing endometriosis-like lesions using knockout (KO) genetic approaches." (PMID 25329068, 2014). "MIF levels are elevated in the peritoneal fluid and peripheral blood of women with endometriosis as well and MIF secretion is enhanced in the peritoneal macrophages of these patients." (PMID 25329068, 2014). "This study provides compelling evidence for the role of MIF in endometriosis development and its possible interest for a targeted treatment of endometriosis." (PMID 25329068, 2014). "It was demonstrated that an increased secretion of MIF by peritoneal macrophages of women with endometriosis and further revealed an increased expression of this factor in eutopic endometrium and initial, active, and vascularized endometriotic lesions." (PMID 23843796, 2013). "Macrophage migration inhibitory factor (MIF), which is markedly upregulated in active endometriosis lesions, also contributes to angiogenesis." (PMID 23766765, 2013). "Our previous studies showed a marked increase in macrophage migration inhibitory factor (MIF) in eutopic endometrial tissue of women with endometriosis, which varied according to the disease’s stage and major symptoms." (PMID 22649515, 2012). "Our previous studies showed an increased secretion of MIF by peritoneal macrophages of women with endometriosis and further revealed an increased expression of this factor in eutopic endometrium and initial, active and vascularized endometriotic lesions." (PMID 22649515, 2012). "The present study was therefore designed to evaluate the efficacy of a specific MIF inhibitor called ISO-1 as a potential treatment for endometriosis using an in vivo model of endometriosis." (PMID 22649515, 2012).
endometriosis (continued). "However, the anti-Sm MIF values were higher in the endometriosis group(16.0±10.8 x 11.7±3.4, p=0.007)." (PMID 39540605, 2024). "According to this study, MIF may be a potential serum biomarker to be used in the diagnosis of endometriosis and the detection of its severity." (PMID 36865552, 2023). "Mahdian and associates reported elevated MIF and CD74 mRNA expression in ectopic lesion tissue compared to eutopic endometrium from both control and patients with endometriosis, while we reported elevated CD74 protein expression and localization to glandular epithelium." (PMID 35885004, 2022). "Alternatively, other receptors capable of binding with MIF-CD74 complexes, such as CD44 could also contribute to MIF signaling in endometriosis." (PMID 35885004, 2022). "Indeed, the literature reports a key role for MIF in the development of endometriosis, especially in the early stages of this disease." (PMID 34769130, 2021). "MIF is positively correlated with the severity of bladder pain, endometriosis, and osteoarthritis." (PMID 34104585, 2021). "Studies have reported higher concentrations of MIF in eutopic and ectopic endometrial tissue, peritoneal fluid, and the peripheral blood of endometriosis patients, while a positive correlation has been observed between its expression and serum estradiol levels." (PMID 34769130, 2021). "Also, significant increase in the levels of IL-6, IL-8 and MIF protein in FF of endometriosis group was detected in comparison with normal women (p<0.05)." (PMID 33209739, 2020). "Moreover, MIF contributes to development of endometriosis, and MIF expression is increased in the endometrium of adenomyosis women." (PMID 32719721, 2020). "Results would be more representative of the targeted population if a relationship between MIF and menstrual cycle phase was proven or refuted and by a cohort design to establish the accuracy of serum MIF to predict endometriosis among symptomatic women and detect the real prevalence of the disease." (PMID 32883256, 2020). "Serum MIF might be a promising marker not only for noninvasive diagnosis of endometriosis but as a target for detecting severity as well." (PMID 32883256, 2020). "For example, endometriosis may impair sperm mobilization through macrophage-secreted IL-1, IL-6, and macrophage migration inhibitory factor (MIF)." (PMID 30104541, 2018). "Yang and colleagues demonstrated that, in patients with endometriosis, MIF could stimulate endothelial cell proliferation." (PMID 26949527, 2016). "Furthermore, add-back of MIF to MIF-KO animals led to a significant increase in the number and size of endometriosis-like lesions." (PMID 25329068, 2014). "Our previous studies showed a positive correlation between MIF levels and endometriosis." (PMID 25329068, 2014). "However, further studies will also be necessary to evaluate the effects of ISO-1 with endometrial tissue from women with endometriosis since it differs from normal endometrium and showed an increased expression of MIF." (PMID 22649515, 2012). "Based on these findings, we hypothesize that MIF may and via different direct and indirect mechanisms play an important role in the development of endometriosis." (PMID 22649515, 2012). "Taken together, these findings strongly suggest that targeting MIF, using specific inhibitors, may represent an interesting strategy for treating endometriosis." (PMID 22649515, 2012). "MIF was also overproduced by activated peritoneal macrophages of women with endometriosis." (PMID 22649515, 2012). "Moreover, either local peritoneal fluid or systemic circulating levels of MIF were found to be higher in women with endometriosis and appeared to depend on the disease’s stage and major clinical symptoms (pain and infertility)." (PMID 22649515, 2012).
endometriosis (continued). "Therefore, our data demonstrating for the first time that ISO-1, a specific antagonist of MIF, effectively interferes with the growth and progression of established endometriosis lesions in vivo, supports a potential therapeutic interest for this molecule." (PMID 22649515, 2012). "A case-control study demonstrated that the macrophage migration inhibitory factor (MIF) protein level was significantly higher in patients with endometriosis compared to those in the control group, and this biomarker was associated with the severity of endometriosis." (PMID 36865552, 2023). "Also, we previouslyshowed the over-expression of MIF in ectopic tissuesfrom endometriosis patients." (PMID 32347038, 2021). "Moreover, the level of serum MIF differed according to the stage of endometriosis with progressive increase with advancing stage (stage I 1.3 ± 1.03 pg/ml-75 patient, stage II 1.7 ± 1.57 pg/ml − 21 patient, stage III 2.1 ± 1.19 pg/ml – 39 patient, and in stage IV 3.2 ± 2.6 pg/ml – 15 patient)." (PMID 32883256, 2020). "Interestingly, endometriosis-like lesions developed in MIF-KO mice showed a significant down-regulation of BCL2, which promotes cell survival, but no noticeable change in the expression of the apoptotic BCL2-family member BAX, which binds to BCL2 and counteracts its apoptosis-preventing effects." (PMID 25329068, 2014). "MIF expression is particularly elevated in active and early stage endometriotic lesions and significantly upregulated in eutopic endometrium from women with endometriosis, where it varies with the stage of the disease and correlates with its major clinical symptoms, namely infertility and pain." (PMID 25329068, 2014). "We present the first data on disease severity-associated changes in the serum levels of the growth factor EGF, the inflammatory cytokines MIF and IL-6, and the inhibitory sensory neuropeptide SOM in patients with endometriosis." (PMID 40724945, 2025). "The transcriptional activity of a number of proinflammatory cytokines/chemokines, such as IL-1, IL-6, IL-8, TNF-α, RANTES, MIF and ICAM1, is activated by NFκB signaling, demonstrating the key role of NFκB in the inflammatory response in endometriosis." (PMID 36359004, 2022). "CXCR4 is capable of forming dimers with MIF-bound CD74; however, the majority of the studies which have evaluated CXCR4 in the context of endometriosis have been evaluating it as a receptor for CXCL12." (PMID 35885004, 2022). "Macrophage migration inhibitory factor (MIF) and monocyte chemoattractant protein-1 (MCP-1) are among the most potent factors responsible for endometriosis-related inflammation." (PMID 34769130, 2021). "Our study showed a significant increase of serum MIF in endometriotic patients that is correlated with disease stage, pain, and infertility and could be probably a promising marker not only for noninvasive diagnosis of endometriosis but as a target for detecting severity as well." (PMID 32883256, 2020). "Macrophage migration inhibitory factor (MIF), is one of a non-invasive blood biomarkers that was expressed in endometriosis and has been suggested to have a pivotal role in the pathogenesis of endometriosis as well as infertility and pelvic pain." (PMID 32883256, 2020). "Furthermore, the cutoff value of serum MIF in our study of 0.85 pg/ml achieved reliably high sensitivity, specificity, positive and negative predictive values, demonstrating the efficiency of the tested marker in diagnosing patients with endometriosis accurately." (PMID 32883256, 2020). "Recent reports have shown a relationship between the production of VEGF, macrophage migration inhibitory factor (MMIF), hypoxia-inducible factor-1 a (HIF-1α) and the stage of endometriosis, as well as the severity of dysmenorrhea." (PMID 32069859, 2020).
endometriosis (continued). "Therefore, our data using a MIF-KO and WT control mice models and showing for the first time that MIF may be required for ectopic endometrial tissue growth and progression of endometriosis lesions in vivo, argues in favor of the possible therapeutic interest for this molecule." (PMID 25329068, 2014). "In conclusion systemic EGF, MIF, IL-6, and SOM might have a contribution to the development and symptomatology of endometriosis, but further rigorous and standardized research is needed to clarify their roles in disease development." (PMID 40724945, 2025). "Increased serum, but not tissue, MIF concentrations were detected in stages I–IV in patients with mild and severe endometriosis, with the highest levels observed in stages III and IV, as well as in patients not receiving oral contraceptives." (PMID 40724945, 2025). "Macrophage migration inhibitory factor (MIF) is the most potent factor responsible for endometriosis-related inflammation, as a significant increase in MIF concentrations has been reported in the endometrial tissue of women with endometriosis." (PMID 38275362, 2023). "The level of E2-induced MIF upregulation was significantly higher in endometrial cells from women with endometriosis than in cells from women without endometriosis." (PMID 38275362, 2023). "Several studies as wellas our group suggested that mRNA and plasma levelsof MIF are increased in the ectopic and eutopic tissuesof endometriosis patients but no geneticvariation was described." (PMID 32347038, 2021). "Women with endometriosis showed more than double-fold increase in serum MIF than non-endometriotic matched women (1.75 ± 1.48 pg/ml vs 0.51 ± 0.45 pg/ml respectively), with a statistically significant difference between groups (p < 0.001)." (PMID 32883256, 2020). "In addition to MIF and PGE2, the ER-β pathway has emerged as a potential target for endometriosis treatment." (PMID 26949527, 2016). "More recent focus has turned toward MIF and PGE2 as potential targets for endometriosis treatment." (PMID 26949527, 2016). "We discuss emerging data on the role and inter-relationship among macrophage migration inhibitory factor (MIF), prostaglandin E2 (PGE2), and estrogen receptors alpha (ER-α) and beta (ER-β), and the potential utility of targeting these factors in endometriosis treatment." (PMID 26949527, 2016). "The action of MIF could be explained by the expression of its receptor, CD74, which was expressed in endometriosis-like lesions." (PMID 25329068, 2014). "Interestingly, selective inhibition of MIF using a specific inhibitor (ISO-1) in WT mice led to comparable outcomes, whereas MIF-add back to MIF-KO animals significantly increased endometriosis-like lesions' size and number." (PMID 25329068, 2014). "Other proangiogenic factors, namely, IL-8, hepatocyte growth factor (HGF), erythropoietin, angiogenin, macrophage migration inhibitory factor, neutrophil-activating factor, and TNF-α, are all found at increased concentrations in the peritoneal fluid of patients with endometriosis." (PMID 23766765, 2013). "Our studies led to the detection of a marked increase in the expression of macrophage migration inhibitory factor (MIF) in the eutopic endometrium, the peripheral blood and the peritoneal fluid of women with endometriosis, and in early, vascularized and active endometriotic lesions." (PMID 22649515, 2012). "Endometriosis is considered an inflammatory disease, due to increased levels of activated macrophages and cytokines such as interleukins (IL-6, IL-8, IIL-1β), tumor necrosis factor-alpha (TNF-α), and macrophage migration inhibitory factor (MIF), in the peritoneal fluid of affected women." (PMID 32143439, 2020). "In addition, we showed that endometriosis-like lesions and mouse endometrial tissue before inoculation (data not shown)were receptive to MIF because of the expression of its receptor CD74, as analyzed by immunohistochemistry." (PMID 25329068, 2014).
endometriosis (continued). "However, our findings supported by previous studies of a significant difference between endometriotic patients with and without pelvic pain could elucidate the possibility that MIF may predict the severity of endometriosis." (PMID 32883256, 2020). "Thus, the lack of MIF led to a decreased expression of VEGF and COX2 in endometriosis-like lesions." (PMID 25329068, 2014).